IL6 (interleukin 6)
Diseases named in the same sentence as IL6 in open-access papers (continued):
Sharing a sentence is not in itself a finding about the gene and the disease.
COVID-19 (continued). "There was a significant increase in the concentration of 40 cytokines/chemokines in a conditioned medium, including TNF-α, IFN-α, IL-6, and IL-1a, which corresponded to the cytokine profile in patients with severe manifestation of COVID-19." (PMID 36290634, 2022). "In that paper, regarding IL-6 levels in COVID-19 versus other disorders, the authors demonstrated that the estimated pooled mean for IL-6 concentrations in all COVID-19 patients, both severe and critical, was only 36.7 pg/mL." (PMID 36289881, 2022). "In a recent systematic review and meta-analysis including 25 COVID-19 studies and 1245 patients, among whom 650 with severe and 367 with critical disease, the authors analyzed the serum level of IL-6 and other inflammatory cytokines." (PMID 36158866, 2022). "Studies show that older patients with COVID-19 had higher rates of lymphopenia and the elevation of inflammatory markers such as IL-6 and CRP, which are significantly correlated with disease severity." (PMID 36072602, 2022). "The systemic inflammation elicited by COVID-19, increases the levels of several inflammatory molecules, including C-reactive protein, IL-1β, IL-2, IL-6, IL-8, IL-10, and TNF-α." (PMID 36439786, 2022). "The elevated levels of inflammatory markers, including C-reactive protein, ferritin, interleukin-1B, and interleukin-6 represent the signature of a severe COVID-19 phenotype." (PMID 36431059, 2022). "In agreement with previous studies, we found that severe COVID-19 patients had elevated serum levels of IL-1α, IL-1β IL-6 and IL-18." (PMID 36142255, 2022). "Severe COVID-19 is known to cause a cytokine storm, in which over-activated lymphocytes secrete many cytokines such as interleukins (ILs); (IL2, IL6, IL7, etc.), and tumor necrosis factor (TNF)." (PMID 35615724, 2022). "Cannabidiol (CBD) was shown to reduce the production of IL-6 and IL-8 in rheumatoid arthritis synovial fibroblasts and was suggested to be added to anti-viral therapies to alleviate COVID-19-related inflammation." (PMID 36559009, 2022). "Plasma levels of HS, HA, IL-1β and IL-6 in addition to increased lipid peroxidation have been observed in COVID-19 patients." (PMID 35742845, 2022). "The role of IL-6 in the disease progression of COVID-19 has been widely recognized, and IL-6 blockade possibly reduce the systemic inflammation." (PMID 35248063, 2022). "In our study, COVID-19 severity correlated positively with serum levels of IL-6, and groups 4 and 5 had mean serum IL-6 levels above 150 ng/l." (PMID 35676519, 2022). "The mean values of AST, total bilirubin, CRP, PCT, and IL-6 were significantly higher in the dead patients compared to the COVID-19 survivors (p < 0.05)." (PMID 36366457, 2022). "Recent works describe vitamin D deficiency affects cytokine synthesis, such as IL-6, IL-8, IL-12, TNF alpha, and IFN-gamma, altering cytokine storm in severe COVID-19 patients." (PMID 36293182, 2022). "The possible COVID-19 pain pathway pathomechanism engaging interleukin (IL)-1, IL-6, and tumor necrosis factor (TNF) alpha aided with a cortical spreading depression disturbing the hypothalamus is also described in this study." (PMID 36284805, 2022). "Even early cases of COVID-19 exhibited a cytokine storm, with interleukin-6 (IL‐6) playing a particularly harmful role." (PMID 35930243, 2022). "IL-6 is a major cytokine involved in the immunopathophysiology of COVID-19, a characteristic biomarker of cytokine storm and a therapeutic target to reduce inflammation and disease symptoms." (PMID 35992174, 2022). "A concentration of more than 37 pg/ml of IL-6 was reported to be predictive of COVID-19 severity and death, which is far higher than the concentration level of IL-6 found by our study." (PMID 36184636, 2022). "A different investigation with 21 COVID-19 cases found that severe cases had greater levels of IL-2R, IL-6, IL-10, and TNF-α than moderate cases." (PMID 36675695, 2022).
COVID-19 (continued). "We identified SARS-CoV-2 dsRNA sequences in COVID-19 plasma exosomes, which stimulated the production of IL-6, IL-8, TNF-α and other cytokines by PBMC from healthy donors." (PMID 36526691, 2022). "TCZ is a neutralizing antibody against IL-6 and IL-6R and blocks both classical and signal transduction pathways, and it is currently the most preferred IL-6 inhibitor in the treatment of patients with COVID-19/ARDS." (PMID 36115998, 2022). "Since blocking IL-6 met with limited success in COVID-19 patients, anti-TNF therapy has been recently considered as a means of reducing inflammation in COVID-19." (PMID 34983527, 2022). "IL-6 and IL-8 are prominent cytokines in the ‘cytokine storm’ characteristic in severe COVID-19 patients and are secreted from alveolar epithelial cells during the disease." (PMID 36559009, 2022). "It has been shown in several clinical studies that IL-6 is a key driver of disease progression in COVID-19, mediating many of the symptoms of a ‘cytokine storm’, in which an amplified immune response can result in multi-organ dysfunction." (PMID 35742845, 2022). "In patients with COVID-19 and other respiratory infections, inflammatory biomarkers harbour strong prognostic information, particularly IL-6 and CRP." (PMID 35622838, 2022). "The inflammatory markers CRP, TNFa, IL6, and ferritin were all elevated in COVID-19 patients at admission, and TNFa showed significant correlation with ANGPT2 (p < 0.01)." (PMID 35740360, 2022). "As discussed, cytokine activation appears to be a prominent feature of severe COVID-19 illness with marked elevations of IL-6 along with other inflammatory markers." (PMID 35402051, 2022). "Recently, some studies have indicated high levels of IL-6 production in patients with COVID-19 at the acute and final stages." (PMID 35815275, 2022). "Serum levels of IP-10, CRP, IL-10, IFNγ, IL-13, IL-17α, IL-23, IL-6 were particularly upregulated in COVID-19 patients compared to controls." (PMID 36554094, 2022). "Patients with COVID-19 have positively correlated with systemic elevation of pro-inflammatory cytokines IL-6 and TNF-α." (PMID 35783877, 2022). "Considering that COVID-19's cytokine storm presents with an elevation of IL-6, TNF-a, and IL-1ß and that pathophysiology of myalgia also involves these cytokines, it seems reasonable to associate SARS-CoV-2 infection with myalgia." (PMID 35223956, 2022). "In particular, IL-6 in the serum of pregnant women with COVID-19 increases by 2.9 when compared with controls (p < 0.0001), while IL-6 in COVID cord blood increases 3.6 times when compared with controls (p < 0.001)." (PMID 35408809, 2022). "Collectively, we suggest a distinct signaling pathway and/or cells for the induction of NP from those of CRP and IL-6 in patients with COVID-19." (PMID 35529699, 2022). "The highest IL-6 expression was observed in severe COVID-19 patients who had the lowest NRF2 expression." (PMID 36377893, 2022). "Predictors of disease severity include ferritin, TNF-α, IL-8, IL-1β and IL-6, suggesting that hyperinflammation is driving COVID-19 severity and death." (PMID 35244141, 2022). "Circulating IL-6 has been related to COVID-19 severity in a number of studies and a comprehensive meta-analysis, and its elevated levels associate with respiratory failure in COVID-19." (PMID 36009555, 2022). "IL-6 and tumor necrosis factor (TNF)-α participate in COVID-19-induced cytokine storm, causing endothelial cell damage and upregulation of plasminogen activator inhibitor-1 (PAI-1) levels." (PMID 35784318, 2022). "Most investigations regarding IL-6 in SARS-CoV-2 infection have demonstrated that IL-6 increases prior to ARDS in critical COVID-19 patients and that elevated IL-6 levels were predictors of the need for mechanical ventilation." (PMID 35634332, 2022). "Severe COVID-19 was associated with hyper inflammation and supported by the concomitant upregulation of Gal-3, TNF-α, and IL-6 in lobar and bronchial pneumonia." (PMID 35897786, 2022).
COVID-19 (continued). "A pathologic hallmark of severe COVID-19 cases is the onset of inflammatory “cytokine storm”, marked by elevated IL1B, TNFA, CCL2, IL6, MIP1A, and IL10 in the plasma." (PMID 35740365, 2022). "Next, we studied the correlation between BiP and IL-6 levels, the most widely used inflammation and severity marker for COVID-19." (PMID 36466830, 2022). "For this reason, among others, some authors have tried to find a relationship between the concentration of CXCL10 and IL-6 in COVID-19 patients." (PMID 35409036, 2022). "In summary, they showed that systemic levels of IL-6 in patients with COVID-19 were about 12 times lower than in ARDS, about 27 times lower than in patients with sepsis, and as much as 100 times lower than in CRS." (PMID 36233040, 2022). "IL-6 levels in the circulation and bronchoalveolar lavage fluid of patients with COVID-19 progressively increase with disease severity, reaching their peaks in critically-ill patients." (PMID 35340805, 2022). "They differently altered cytokine response in K18-hACE2 mice, and open reading frame 3a (ORF3a) deletion resulted in the lowest IL-6/IL-10 ratio, a marker of cytokine storm in COVID-19." (PMID 35632736, 2022). "Clinical observations indicate that COVID-19 patients manifest an acute elevation of serum levels of inflammatory mediators, such as IL-6, IL-1, TNF-α, and JAK." (PMID 36366444, 2022). "Most patients had elevated inflammatory markers like CRP and ferritin, which are suggested predictors for COVID-19 severity, and are reported to correlate with d-dimer and IL-6 levels." (PMID 35059221, 2022). "In COVID-19 patients with acute respiratory distress syndrome (ARDS), ATII increases NOX and causes vasoconstriction and thrombosis via ROS, IL-6, tumour necrosis factor-Alpha (TNF-α), and other cytokines." (PMID 35639261, 2022). "During the current pandemic, the vast majority of COVID-19 patients experienced mild symptoms, but some had a potentially fatal aberrant hyperinflammatory immune reaction characterized by high levels of IL-6 and other cytokines." (PMID 35746559, 2022). "In terms of a potential prognostic biomarker for COVID-19 patients, it has been found that levels of IL-6 were increased at admission for patients with neurological disorders." (PMID 35665037, 2022). "The differences between the median IL-6 blood level were significant not only between patients with severe COVID-19 and those with mild and moderate forms but also between subjects with mild and moderate clinical pictures." (PMID 33983525, 2022). "Comparison of cytokine levels showed that patients with severe acute COVID-19 had significantly higher levels of IL-6 (p=0.0260) as compared to mild/moderate group." (PMID 35846757, 2022). "It is reported that patients with COVID-19 symptoms have higher levels of cytokines and inflammatory markers such as IL-6, IL-8, IL-1β, IL-10, IL-12, and IFN-γ." (PMID 35847031, 2022). "In patients with COVID-19, the mean VR [2.05 (0.42) vs. 1.77 (0.24), P = 0.001] and IL-6 [721.27 (645.44) vs. 148.89 (179.80), P < 0.001] were significantly higher in those who developed a PE." (PMID 35308552, 2022). "The inhibitor of IL6, Tocilizumab, has also been explored as a therapeutic agent to overcome cytokine storm in severe COVID-19 patients with varying outcomes." (PMID 36518355, 2022). "Although the importance of D-Dimer and IL-6 as predictors of COVID-19 mortality has been noted by others, ours is the first study to confirm the robustness of this association independent of respiratory mechanics variables such as VR and PaO2/FIO2 ratio." (PMID 35308552, 2022). "Our data imply that COVID-19 is characterized by a broad and strong innate and adaptive immune response orchestrated by IL-6 and other mediators." (PMID 35256646, 2022).
COVID-19 (continued). "Therefore, two explanations may justify the increased PCT levels associated to severe COVID-19 outcome: first, the high serum levels of cytokines like IL-6 and TNF-α from “cytokine storm” that may promote the increase in PCT levels; second, the presence of a bacterial co-infection." (PMID 35355599, 2022). "This feedback loop is termed the IL-6 amplifier, which is a key player in autoimmune disorders, oncogenesis, and COVID-19-mediated ARDS and multiorgan failure." (PMID 35563697, 2022). "Numerous cytokines and chemokines are profoundly elevated in patients with severe COVID-19, including cytokine IL-6, TNFα, and chemokine IL-8." (PMID 35277472, 2022). "Among other features, critical COVID-19 is characterized by high circulating levels of interleukin (IL)-1Ra, IL-6, IL-8, TNF-α, and ICAM-1 and low levels of FasL." (PMID 36225555, 2022). "Other therapeutic monoclonal antibodies are directed at proinflammatory cytokines (IL-6, IL-1β, TNF and GM-CSF) to mitigate cytokine storm syndrome (CSS) that is the frequent cause of fatal acute respiratory distress syndromes (ARDS) in COVID-19 patients." (PMID 35743031, 2022). "High levels of IL-6 have previously been demonstrated in FIP ascites, and, likewise, elevated IL-6 levels appear associated with disease severity and outcome in COVID-19 patients." (PMID 35336888, 2022). "In COVID-19 patients, there was a correlation between elevated IL-6 and D-dimer levels with disease deterioration." (PMID 37841828, 2022). "Moreover, IL-6 inhibiting drugs may predispose COVID-19 patients to invasive mucormycosis." (PMID 35386908, 2022). "One of the most important cytokines is interleukin 6 (IL-6), whose levels correlate with the severity of COVID-19." (PMID 36079820, 2022). "This is significant because TLR7/8 activation of NF-κB increases cytokine production and, in conjunction with inflammasome activity, NF-κB drives an axis of IL-1β, IL-6, IL-12, TNFα, and Th1 T-cell hyperinflammation as part of COVID-19 immunopathology." (PMID 35261923, 2022). "So, the current study evaluated the cardiac biomarkers and expression analysis of IL-1, IL-6, IL-10, IL-17 and IL-25 among COVID-19 patients from Pakistan." (PMID 36298704, 2022). "Use of LMWH was found to reduce serum IL-6 levels, which are a key factor in patients with severe COVID-19, and to reduce TNF-α levels." (PMID 34406312, 2022). "For example, increased levels of IL-6 were found to be highly associated with disease severity of COVID-19 patients, especially with ARDS, suggesting the important role of IL-6 in the pathogenesis of COVID-19." (PMID 36290585, 2022). "At early post-acute COVID-19 follow-up, a substantial portion of study participants presented with low-grade thrombo-inflammation, as reflected by increased IL6, neopterin, pro-calcitonin, C-reactive protein (CRP) or d-dimer blood concentrations." (PMID 35736479, 2022). "Recent research has discovered that elevated plasma levels of IL-1β and IL-6 expression are a typical sign of the cytokine storm generated by new coronavirus pneumonia (COVID-19)." (PMID 35669119, 2022). "Incidence of the secondary outcome was 23% in COVID-19 patients with high IL-6 levels (above the median of 20.77 pg/ml) vs. 5% in patients with low IL-6 levels (log-rank p = 0.002, HR 4.62 [95%CI, 1.55–13.73], p = 0.006)." (PMID 35622838, 2022). "IL-6 levels were greater in severe instances compared to moderate COVID-19 patients, but IL-4, IL-18, and IL-35 between both illness categories were at close levels." (PMID 36675695, 2022). "Changes in laboratory and electrocardiographic parameters in patients with COVID-19 (n = 33), during active disease and after therapeutic interventions resulting in a >60% decrease in IL-6 level when compared to the baseline." (PMID 35665254, 2022). "Second, baseline IL-6 is a promising predictor of disease severity and mortality during hospitalization of COVID-19 patients." (PMID 35248063, 2022).
COVID-19 (continued). "Among the inflammatory mediators released by immune cells, the cytokines IFN-α, IFN-γ, IL-1β, IL-6, IL-12, IL-18, IL-33, TNF-α and TGF-β are highlighted, and altered levels are associated with different clinical features of COVID-19." (PMID 35846757, 2022). "Patients with severe COVID-19 to cause a large number of pro-inflammatory macrophages were found in bronchoalveolar lavage fluid and released a large number of IL-1, TNF-α, IL-6 IL-8, CSF, and MCP-1 to induce cytokine storm." (PMID 36381194, 2022). "Dynamic observation of IL-6 levels is also helpful in understanding the progression of COVID-19 and the response to treatment." (PMID 35308307, 2022). "Overall, the summary estimates of all analyses suggested that IL-6 was an independent prognostic factor toward COVID-19 severity and mortality." (PMID 35215138, 2022). "Recent research suggested that the inflammation cascade in severe COVID-19 patients with respiratory failure are intricately associated with an increase in TNF-α, IL-6 and MCP-1." (PMID 36135185, 2022). "From the early stages of the pandemic, IL-6 has been a well-documented biomarker of disease severity and poor prognosis, and considered among the most promising targets in the treatment of the COVID-19 cytokine storm." (PMID 35340805, 2022). "Serum ferritin, CRP, and IL-6 levels were high in 295 (71%), 253 (61%), and 153 (37%) patients respectively, indicative of severe COVID-19 illness." (PMID 35433146, 2022). "Oral inhibitor of JAK and stops the IL-6 / JAK / STAT3 pathway that can significantly reduce IL-6 levels like upadacitinib and it can be a good treatment option for COVID-19." (PMID 36111104, 2022). "GDF15 in severely affected COVID-19 patients is more specific than IL-6, CRP, ferritin and D-dimer in detecting the early stage of COVID-19 severity and admission to the intensive care unit (ICU)." (PMID 36140453, 2022). "White blood cell count (WBC) to lymphocyte ratio was over two-times higher, D-dimer over four-times higher, ferritin three-times higher and IL-6 over twenty-times higher in patients with COVID-19 as compared to patients with ARDS from other etiologies." (PMID 35308552, 2022). "According to a systematic review and meta-analyses of 10 cohort studies, including 1798 patients, elevated levels of IL6 were observed in patients with COVID-19." (PMID 35619180, 2022). "The main aim of this study was to examine the association of Nrf2 and HO-1 in COVID-19 patients with the disease severity and the markers of the hyperinflammatory response (C-reactive protein-CRP, IL-6, ferritin)." (PMID 36422196, 2022). "This is consistent with previous studies correlating IL-6 levels with hyponatremia in COVID-19 and other inflammatory conditions, possibly through stimulation of pituitary ADH secretion." (PMID 36714113, 2022). "It is also suggested that, like COVID-19, severity of blood-stage malaria correlates with the circulating IL-6 levels." (PMID 36415655, 2022). "Our findings are consistent with medical literature data, and several other studies reported higher IL-6 levels in severe COVID-19 cases and higher CRP in correlation with disease severity or adverse outcomes." (PMID 36142336, 2022). "Our results confirmed the results of previous studies that systemic levels of proinflammatory cytokines IL-1 and IL-6 are rising during the progression of COVID-19 suggesting on ongoing development of inflammation." (PMID 35075140, 2022). "IL-6 level was reported to be associated with patients' clinical manifestations, including body temperature and blood oxygen saturation, and COVID-19 patients with higher IL-6 levels had a poorer prognosis." (PMID 35540724, 2022). "Numerous scientific articles have reported on the association of IL-6 and TNF-α with the severity and mortality of COVID-19." (PMID 36359509, 2022). "Comparing IL-1 and IL-6 inhibitors were reported in an observational study in Italy COVID-19 patients with severe respiratory dysfunction and hyperinflammation." (PMID 35619180, 2022).